C8orf17 (chromosome 8 putative open reading frame 17)
Description:
May be involved in cell survival, proliferation and progression of cancer cells.
Synonyms: MOST-1; MOST1
Gene: Gene on chromosome 8 (139,931,172 to 139,933,942, forward strand). Ensembl gene ENSG00000250733.
Subcellular location: Cytoplasm; Microsome membrane; Endoplasmic reticulum membrane
Diseases named in the same sentence as C8orf17 in open-access papers:
C8orf17 is named in the same sentence as 1 disease in open-access papers, as found by Europe PMC text mining. Sharing a sentence is not in itself a finding about the gene and the disease. The quoted sentences say what the papers report.
cancer (1 paper, 2013). A tumor composed of atypical neoplastic, often pleomorphic cells that invade other tissues. "In this context, telethonin has been reported to interact with MOST1 (C8orf17), a protein ubiquitously expressed in many cancer cell lines." (PMID 23065501, 2013).